CTLA4 (cytotoxic T-lymphocyte associated protein 4)
Diseases named in the same sentence as CTLA4 in open-access papers (continued):
Sharing a sentence is not in itself a finding about the gene and the disease.
tumor (continued). "Targeting tumor-specific T cells, therapeutic interceptions that inhibit receptors, including PD1 (pembrolizumab, nivolumab), CTLA4 (ipilimumab, tremelimumab) and LAG3 (BMS-986,016), have been approved or are in clinical trials for the treatment of various cancer types." (PMID 33228738, 2020). "Furthermore, VEGF-A induces the upregulation of multiple immune checkpoints, such as PD-1, CTLA4, TIM3 and LAG3, in tumor-infiltrating CD8+ T cells, and VEGF-silencing potentiates tumor control mediated by the PD-1 blockade." (PMID 32231117, 2020). "Tumor cells produce immunosuppressive cytokines (e.g., IL-10, TGF-β, PGE2), recruit Tregs, activate negative regulatory pathways (e.g., PD-1/PD-L1, CD80/CTLA4) or express immunomodulatory molecules (e.g., IDO), thus establishing an immunosuppressive microenvironment." (PMID 32054102, 2020). "The co-blockade of CTLA-4 and LAG-3 or PD-1 and LAG-3 showed better therapeutic efficacy through increased CD8+T cells with/without the reduction of Tregs in the tumor, compared to single CTLA-4 or PD-1 targeting." (PMID 32508809, 2020). "In agreement with previous studies, the absence of IDO1 did not prevent tumor growth, but increased the efficacy of anti–CTLA-4 antibody that was maintained in the presence of Tα1." (PMID 32817121, 2020). "For example, expression of PD-1, TIM-3, LAG-3, and CTLA4 is significantly higher on CD8+ and CD4+ T-cells in HCC tissue than those in non-tumor tissues or peripheral blood, and dendric cells (DCs), monocytes, and B cells in tumors express ligands for these receptors." (PMID 32443599, 2020). "However, the tumor volume of LLC-sgAtrx was significantly decreased after anti-PD1 and anti-CTLA4 intervention compared with the control group." (PMID 33409155, 2020). "Recently, complementary activity of CTLA4 and PD‐1 checkpoint inhibitors in MM treatments has been demonstrated, and a combination of stereotactic body RT, anti‐CTLA‐4, and anti‐PD‐1 ligands promoted tumor responses in murine B‐16 models and patients." (PMID 32524777, 2020). "Accordingly, CTLA-4 prevents activated T cells to infiltrate peripheral nonlymphoid organs, whereas antibody-mediated inhibition of CTLA-4 increases the motility of tumor infiltrating cytotoxic T cells." (PMID 34396271, 2020). "However, immune checkpoint genes including IDO1, HAVCR2, PDCD1LG2, CD274, CTLA4, and TIGIT were significantly up-regulated in tumor samples (fold change >1.30, FDR q ≤ 1.0e-5)." (PMID 33257699, 2020). "In addition, high amount of tumor-derived VEGF induced high level of PD1, CTLA4, TIM3, and LAG3 expression which were makers of exhaustion on the surface of CD8+ T cells, contributing to resistance in anti-PD1 treatment." (PMID 32793604, 2020). "Kit+ CD11b− NK cells also reported upregulation of CTLA-4; however, its involvement in tumor progression in NK cell-controlled cancers has not been investigated." (PMID 32117298, 2020). "It has also been suggested that CTLA-4 can mediate negative signals into tumor cells, comparable to those observed in resting T-lymphocytes, thus inhibiting tumor cell proliferation and/or inducing apoptotic cell death." (PMID 32123292, 2020). "In addition, TOX knockdown in TI CD8+ T cells from human tumor reduced the number of cells expressing PD-1, TIM-3, TIGIT, and CTLA-4." (PMID 32111241, 2020). "As such, investigations into the expression pattern and function of CTLA-4 in non-tumor and non-hematopoietic tissue is warranted." (PMID 33384695, 2020). "The addition of anti-CTLA-4 antibody during the rapid expansion did not change the tumor reactivity of TILs and CD8+ T cells." (PMID 32127601, 2020). "In mouse ovarian cancer model, MDSC enhanced the expression of CD80 through direct contact with tumour cells, and CD80 could bind to CTLA-4 on Tregs to enhance the immunosuppressive function of Tregs." (PMID 32680511, 2020).
tumor (continued). "Although elevated CTLA-4 levels are beneficial for tumors to evade immune surveillance, they can increase sensitivity to CTLA-4 blockade by relieving immunosuppression of the gut and tumor tissues." (PMID 32522267, 2020). "In another study, it was demonstrated that most of the intra-tumor CD4+Foxp3+ Treg cells have a Helios+, CTLA-4+, and CD39+ phenotype, but 30% of CD4+Foxp3− cells also expressed markers associated with regulatory functions, including CD25, LAG-3, and latency-associated peptide (LAP)." (PMID 32674255, 2020). "CTLA4 competes with CD28 receptors for the binding to B7 ligands (CD80 and CD86) on antigen-presenting cells (macrophages, DCs and B cells), as well as TAMs and MDSCs, inhibiting T cell activity and thus promoting tumor progression." (PMID 32823961, 2020). "Treatment with IPI-549 also led to up-regulation of PD-1 and CTLA-4 expression on CD8+ T-cells, suggesting that combining PI3K-γ inhibition with immune checkpoint blockade could provide additional anti-tumor effects." (PMID 33212945, 2020). "In conclusion, we have found that CTLA-4 is expressed at the cell membrane of a subgroup of TNBC tumors and our results provide novel mechanistic data by which CTLA-4 regulates key signal transducers in tumor cells." (PMID 32850353, 2020). "Correlation analyses also demonstrated that CD8+ T-cells, CD8+ Tcm, CD8+ naive T-cells, CD4+ memory T cells, and CD4+ naïve T cells were all positively correlated with expressions of these inhibitory receptors in tumor tissues, especially with PD1 and CTLA4 (P < 0.05)." (PMID 32728493, 2020). "Moreover, nanoscale immunoconjugates (NICs) on a natural biopolymer scaffold, poly(β-L-malic acid), were produced with covalently attached anti-CTLA-4 or anti-PD-1 for systemic delivery across the BBB and activation of local brain anti-tumor immune responses." (PMID 32014107, 2020). "Inhibition of PD-L1, LAG3, and CTLA4 could increase CD8 T cells and CD4 T cells and reduce Tregs, thereby enhancing anti-tumor response." (PMID 33401247, 2020). "Several immunosuppressive mechanisms may be involved in the process, such as overrepresentation of immunosuppressive cells (e.g., Tregs) and increased expression of immunosuppressive molecules (e.g., PD-1, CTLA-4, LAG3, and CD47) in the tumor microenvironment." (PMID 32028264, 2020). "Tumor-derived exosomes were shown to mediate the conversion of CD4+ CD25− T cells into CD4+ CD25high FOXP3+ regulatory T cells with enhanced expression of Fas ligand, IL-10, TGF-β1, CTLA-4, granzyme B, and perforin." (PMID 32499786, 2020). "Later studies showed that anti-CTLA-4 treatment induces a robust increase in both CD4+ and CD8+ T cell populations in several human cancers including lung cancer, thereby limiting T reg infiltration into the tumor bed and increasing T effector to T reg ratio." (PMID 32117295, 2020). "Improved understanding of the immunobiology of cancer tissues and the tumor microenvironment (TIME) has led to the emergence of highly effective anti-cancer therapies related to immune checkpoint blockers (ICB) such as PD1, PDL1, and CTLA-4." (PMID 33216732, 2020). "Since the anti-tumor efficacy of the dual combination therapy (G47Δ-IL12+axitinib) was T cell dependent, it is hypothesized that ICI (i.e., anti-PD-1 or anti-CTLA4) will improve the therapeutic outcome of G47Δ-IL12+axitinib dual combination." (PMID 32050597, 2020). "We observed a significant decrease in viability of renal cell lines after treating with CIK cells (p < 0.0001) in comparison to untreated renal cell lines and anti-PD-1 or anti-CTLA-4 treatment had no remarkable effect on the viability of tumor cells." (PMID 32349280, 2020). "The combination of SLC-0111 with anti-PD1 and anti-CTLA4 in mice bearing orthotopic breast tumors did not lead to visible tumor growth delay." (PMID 32707920, 2020).
tumor (continued). "In this study, the combination of anti‐CTLA‐4 and anti‐PD‐1 monoclonal antibody significantly delayed tumor growth in control mice, but was not effective in β‐catenin–activated mice." (PMID 32875727, 2020). "Treatment with a dual anti-CTLA4 and anti-PD1 blockade induces tumor vessel normalization." (PMID 32138216, 2020). "Immune checkpoints (PD-1, CTLA-4, TIM-3, etc.)serve as a brake on immune cell overactivity and prevent autoimmune reactivity, whereas tumor cells can escape human immune surveillance by upregulating the expression of immune checkpoints, thereby leading to tumor recurrence." (PMID 33643279, 2020). "More recently, we reported that pH-sensitive anti-CTLA-4 antibodies are more effective in ADCC and tumor rejection, which raise the issue as to whether increasing ADCC activity jeopardizes the selectivity of the antibodies." (PMID 31991588, 2020). "Their result showed the administration of combined anti-CTLA-4 therapy (9H10), anti-PD-1 therapy (RMP114), and agonistic anti-4-1-BB therapy (3H3), induced bilateral tumor regression in 40% of mice while the STING agonist CDG added, markedly inhibited the bilateral tumors in 75% of these mice." (PMID 32571374, 2020). "CTLA-4 downregulates T-cell activation and inhibits its anti-tumor immune response by binding to co-stimulatory molecules on DCs (CD40, CD80, and CD86) and suppressing their ability in presenting foreign or tumor antigens." (PMID 32784928, 2020). "Taken together, CRISPR/Cas9-mediated acute Nr2f6 gene ablation in primary mouse T cells prior to ACT appeared feasible for potentiating established PD-L1 and CTLA-4 blockade therapies, thereby pioneering NR2F6 inhibition as a sensitizing target for augmented tumor regression." (PMID 31937317, 2020). "As a result, HLA class I molecule expression appeared a reliable predictive biomarker of tumor response to anti-CTLA-4 mAb ipilimumab but not to anti-PD-1 mAb nivolumab." (PMID 33023239, 2020). "In fact, in the ICIs resistant B16-GM-CSF model, the combination of either an anti-CTLA-4 (9H10 clone, 100 μg/mouse) or an anti-PD-1 (RPM1-14 clone, 250 μg/mouse) (four doses every third day) with IPI-549 significantly delayed tumor growth, compared to ICIs administered as single agents." (PMID 33212945, 2020). "Ipilimumab binds to CTLA-4 on T-cells, which inhibits its ability to bind to CD80/CD86, allowing for the expansion of a repertoire of antigen-specific anti-tumor cytotoxic CD8+ T-cells and CD4+ T-cells, which corresponds to an improved anti-tumor immune response." (PMID 33256089, 2020). "Fc-region–modified anti-CTLA-4 mAb with high antibody-dependent cell-mediated cytotoxicity (ADCC) and cellular phagocytosis (ADCP) activity selectively depleted CTLA-4+Foxp3+ Tregs and consequently expanded tumour antigen-specific CD8+ T cells." (PMID 32680511, 2020). "Analysis of surgical tissues and peripheral blood before and after treatment showed that anti-CTLA-4 treatment could induce ICOS pathway activation, and CD4+ICOS+T cells could produce IFN-γ and recognize tumor antigens." (PMID 32864131, 2020). "Furthermore, more positive results were obtained in tumor-bearing mice treated with a combination of RT, anti-CD40 and anti-CTLA-4/PD-1." (PMID 35582441, 2020). "One of the pharmacodynamically most successful ICI-related approaches to enhancing the anti-tumor immune response consists of interfering with the negative costimulation of T cells, by inhibiting PD-1, PD-L1, and CTLA-4." (PMID 32357515, 2020). "Most interestingly, half of the mice in the group with anti-PD-1/CTLA4 dual blockade did not have detectable luciferase signal at day 49, suggesting complete tumor regression following the combination therapy." (PMID 33177175, 2020). "Therefore, we evaluated the tumor microenvironment of PMBCL and found that compared with DLBCL–NOS, PMBCL had significantly higher levels of PD-L2 expression in B-cells and higher CTLA-4 expression whereas lower PD-1 expression in T-cells." (PMID 32366834, 2020).
tumor (continued). "Anti-tumor activity observed with an ICOS agonist is further enhanced with CTLA-4 and PD-1 blockade in non-clinical models." (PMID 32967162, 2020). "In the CT26 tumor model, stabilization as complete regression of the tumor growth were observed in mice treated with anti-CTLA-4 without sodium butyrate as well as longer survival." (PMID 32358520, 2020). "Anti-CTLA-4, anti-PD-1 and anti-PD-L1 Abs were granted approval from the FDA and European Medicines Agency (EMA) for the treatment of a broad spectrum of neoplastic diseases, in early and advanced settings, because they were shown to elicit durable clinical responses." (PMID 37425217, 2020). "Moreover, a blockade of CTLA-4, a co-inhibitory receptor expressed on CD4+ and CD8+ T cells, can enhance anti-tumor immunity." (PMID 32664564, 2020). "Experiments also found that DNA vaccination targeted CTLA-4 and PD-L1, but not PD-1, eliciting serum-specific antibody production and suppressing the tumor growth in iCCA rats." (PMID 33255375, 2020). "Interestingly, data indicate optimal benefit is in part dependent on sequence of therapeutic administration, with cohorts receiving anti-CTLA-4 post vaccination exhibiting higher levels of CD8+ T cells and increased tumor-specific lytic function." (PMID 32111080, 2020). "We used qPCR to analyze the ALDH3A2, PDCD1, PDCD1LG2, and CTLA-4 mRNA expression levels in 52 tumor tissues, which indicated a negative spatial correlation between ALDH3A2 and PDCD1 (R2 = 0.3576), PDCD1LG2 (R2 = 0.3878), and CTLA-4 (R2 = 0.2556)." (PMID 33148208, 2020). "The 400 mm3 (at start) group treated with the anti-CTLA-4 antibody (10mg/kg, biw, ip) on day nine did not produce anti-tumor activity (P > 0.05), as the tumor volumes were 2313±234 mm3." (PMID 32805718, 2020). "For example, combination of histone deacetylase inhibitor belinostat with anti-CTLA-4, or combination of anti-CTLA-4 plus anti-PD-1 antibodies could lead to complete tumor rejection in a mouse HCC model." (PMID 32899197, 2020). "However, CTLA-4 outcompetes CD28 for CD80/CD86 binding, thereby, inhibiting the downstream TCR signaling and hampering anti-tumor CD8+ T cell function." (PMID 33256089, 2020). "Interestingly, CRC patients display Treg cells with a higher expression of several molecules that correlate with suppression, such as Tim-3, LAG-3, TGF-β, IL-10, CD25, and CTLA-4, and by the BLIMP-1 transcription factor expression in the tumor." (PMID 32674255, 2020). "To study the role of CTLA-4 on TNBC tumors, we explored public data with a tumor purity >60%." (PMID 32850353, 2020). "Approaches of cancer immunotherapy have recently been boosted by the discovery that immune checkpoint-specific monoclonal antibodies (ICmAbs), such as antibodies against CTLA-4, PD-1, and PD-L1, can rescue the adaptive cellular immune response, mostly CTL, kept at bay by the tumor." (PMID 33138029, 2020). "To investigate whether some specific subsets of leukocytes affects anti-CTLA-4 therapy response rates, we used the CIBERSORT algorithm to estimate the fraction of each leukocyte subset in the tumor microenvironment." (PMID 31991588, 2020). "Moreover, the novel mAbs showed a reduced ability to interfere in the binding of CD-80 ligands to CTLA-4 on T cells with respect to Ipilimumab, suggesting that they could allow for anti-tumor effects without the irAEs associated with the potent antagonistic activity of Ipilimumab." (PMID 32781690, 2020). "While this is a widespread finding in patients exhibiting successful tumor responses following immunotherapy with CTLA4-specific with or without PD1-specific antibodies, adverse inflammatory effects are not commonly found in mice treated in a similar way." (PMID 33093155, 2020). "Levels of TIM-3, CTLA-4, TIGIT, TOX, TOX2, and SIRT1 genes in tumor tissue were significantly higher than that of the circulation; their expressions within the TME could be induced by tumor-mediated immunosuppression." (PMID 32393998, 2020).
tumor (continued). "All the INT230-6-treated groups had statistically significant reduced tumor growth compared to the untreated and the CTLA-4 + PD-1 group, where tumors continued to grow without any evidence of regression." (PMID 32599852, 2020). "The immune checkpoint CTLA-4 (cytotoxic T-lymphocyte-antigen 4), which inhibits the co-stimulatory CD28 signal on T cells, has been recently found expressed on other cell populations, such as tumor and natural killer (NK) cells." (PMID 32024070, 2020). "Previous evidence suggested that depleting Treg cells using antibodies against Treg markers (CTLA-4 and OX40) at a single tumor site could generate a systemic anti-tumor response that eliminated disseminated metastatic tumor cells." (PMID 35310881, 2020). "In addition, CD28 and CTLA4 expression has been reported in activated mouse NK cells, the interaction between CTLA4 and CD80 has a direct effect on IFN-γ release by NK cells, and CTLA4 expression has been reported in mouse tumor infiltrating NK cells." (PMID 31898484, 2020). "The inflamed TME was characterized by higher expression of PDCD1, CTLA4, CD28, (PD-L1) CD274, PD-L2, and lower tumor mutation burden than non-inflamed TME." (PMID 32528935, 2020). "Moreover, simultaneous expression of inhibitory receptors such as PD-1, CTLA-4, and TIM-3 correlates with increased T cell dysfunction in cancer and tumor progression." (PMID 32316916, 2020). "None of the evaluable non-responders had a CTLA4+/PD-1+ exhausted CTL signature in tumor samples, rendering the positive and negative predictive value of the test at 100%." (PMID 32681091, 2020). "As such, studies conducted in poorly immunogenic melanoma more than two decades ago showed that, while the tumors did not respond to anti-CTLA4, a combination with a GM-CSF-transduced cellular vaccine induced a tumor response." (PMID 33036244, 2020). "Combining both antibodies, anti-PD-1 and anti-CTLA-4, led to tumor shrinkage in HepFrag tumors, whereas the monotherapy had no beneficial effect on tumor regression." (PMID 31291357, 2019). "In this study, we determined 11 immunomodulators that are involved in tumor escape mechanisms and found 9 immunomodulators (LAG-3, TIM-3, CTLA-4, IFN-γ, ICOS, ICAM-1, TIGIT, NKG2A, and VISTA) that were upregulated in both high-immune score group and high-stromal score group." (PMID 31781309, 2019). "Systemic, i.v. administration of anti-CTLA-4 can also result in activated naïve-T cells in non-tumor draining LNs where non-tumor, self Ags rather than tumor Ags are presented (insert B), and presumably lead to irAEs." (PMID 31754400, 2019). "Third, co-inhibition of PD-1 and CD80, the alternate receptor for PD-L1, using anti-CD80 mAb or a CTLA-4-Ig fusion protein, Abatacept, failed to control tumor escape or prolong survival over PD-1 blockade alone." (PMID 31481761, 2019). "Only, however, in the IT-pIL12/EP-treated mice, was a distinct PD-1loCTLA4lo CD8 population observed, which failed to upregulate PD-1 or CTLA-4 upon infiltration into the antigen-rich microenvironment of the contralateral tumor." (PMID 30323352, 2019). "Moreover, antibiotic use has been correlated with poorer outcome in tumor-carrying mice and metastatic RCC and NSCLC patients treated with anti-PD-1 and anti-CTLA-4 antibodies." (PMID 30887236, 2019). "Notably, CD80 and CD86, which are expressed on both tumor cells and TILs, can interact with CD28 on T cells to activate costimulatory signaling and with CTLA-4 on activated T cells to initiate inhibitory signaling." (PMID 31771653, 2019). "The cell-intrinsic effect of CTLA-4 blockade on effector T cells has been shown in mice and humans to be the primary mechanism for the anti-tumor effect, rather than its effect on Treg cells." (PMID 30788290, 2019). "They correlated the high expression detected to T-cell expression of CTLA-4 and not to the tumour cells." (PMID 31656546, 2019).